EGFR (epidermal growth factor receptor)
Diseases named in the same sentence as EGFR in open-access papers (continued):
Sharing a sentence is not in itself a finding about the gene and the disease.
lung adenocarcinoma (continued). "This retrospective study aimed to investigate this association in advanced lung adenocarcinoma patients with ALK, ROS1, RET rearrangements, and EGFR mutations." (PMID 40751559, 2025). "We investigated lung computed tomography (CT) radiomics features feasibility for brain metastasis (BM) prediction in patients with epidermal growth factor receptor-positive lung adenocarcinoma (LA-EGFRp)." (PMID 41466189, 2025). "The incidence of brain metastasis (BM) in patients with NSCLC can reach up to 50%, with the highest incidence of BM in cases of epidermal growth factor receptor-positive lung adenocarcinoma (LA-EGFRp) at approximately 45–52%." (PMID 41466189, 2025). "Epidermal growth factor receptor (EGFR) mutations and anaplastic lymphoma kinase (ALK) rearrangements are common genetic alterations in lung adenocarcinoma." (PMID 41020204, 2025). "Among EGFR mutations, exon 19 deletions (19Del) and the exon 21 L858R point mutation (21L858R) represent the two most prevalent subtypes, together accounting for the vast majority of EGFR-mutant lung adenocarcinomas." (PMID 41049833, 2025). "The patient underwent three diagnostic revisions: presumed HCC recurrence → metastatic prostate cancer → EGFR-mutant lung adenocarcinoma." (PMID 40740944, 2025). "The study identifies agrin‐EGFR mechanotransduction as a critical driver of lung adenocarcinoma which enhances EGFR signaling through an integrin‐FAK‐actomyosin dependent positive feedback on YAP/TAZ ‐TEAD in response to matrix stiffness." (PMID 40165020, 2025). "For instance, TFF3 promotes EGFR activation by positively regulating YAP, thereby contributing to drug resistance in EGFR-mutated lung adenocarcinomas." (PMID 40003951, 2025). "The top five actionable alterations in lung adenocarcinomas were reported in EGFR (43 %), ALK (5 %), BRAF (5 %), KRAS (5 %), and ROS1 (2 %) genes." (PMID 40821453, 2025). "In the context of EGFR-mutated NSCLC, a study that analyzed 109 patients with lung adenocarcinoma showed that AXL expression correlated with lymph node metastasis and was more frequently detected in EGFR-mutated compared to EGFR wild-type lung tumors." (PMID 40243603, 2025). "In EGFR-mutant lung adenocarcinoma, SIRT5 suppresses CD8+ T-cell recruitment through an ACAT1–NRF2 succinylation axis, providing an additional layer of suppression that limits responsiveness to checkpoint blockade." (PMID 41425553, 2025). "EGFR amplification is considered an on-target acquired resistant mechanism of lung adenocarcinoma treated with EGFR tyrosine kinase inhibitors." (PMID 40310364, 2025). "In summary, the quantitative and qualitative parameters of three-dimensional CT are related to EGFR and ALK gene rearrangements and prognosis in patients with GGO-associated lung adenocarcinoma." (PMID 41020204, 2025). "This study aims to explore the correlation between EGFR mutation status, ALK positivity, and various demographic, radiological, and pathological features of lung adenocarcinoma." (PMID 41378298, 2025). "The presence of TLSs in early-stage EGFR-mutant lung adenocarcinoma was further confirmed using multiplex fluorescent IHC staining." (PMID 40723259, 2025). "We aimed to investigate the variances in the gene signatures of the tumor microenvironment between high-TLS-density and low-TLS-density early-stage EGFR-mutant lung adenocarcinoma." (PMID 40723259, 2025). "The only cell line in this work in which PI3Kα appeared dispensable for EGF-induced PI3K signaling was A549, a lung adenocarcinoma cell line with amplified EGFR." (PMID 39706867, 2025).
lung adenocarcinoma (continued). "Dysregulation of EGFR degradation further accelerates tumorigenesis and advancement, particularly in mutant EGFR-driven lung adenocarcinoma (LUAD)." (PMID 39910656, 2025). "TKIs that target EGFR are the current standard of care for patients with EGFR-mutant lung adenocarcinomas." (PMID 40323013, 2025). "Genetic alterations in key oncogenes have been frequently identified in lung adenocarcinoma (LUAD), including genes encoding epidermal growth factor receptor (EGFR), Kirsten rat sarcoma viral oncogene homolog (KRAS), and anaplastic lymphoma kinase (ALK)." (PMID 40621945, 2025). "For instance, the activating mutations of the epidermal growth factor receptor (EGFR) gene (EGFR-mut) have been observed in 15% (Europe) to 62% (Asia) of lung adenocarcinoma cases." (PMID 39858622, 2025). "Univariate analysis of the effects of EGFR gene mutation and ALK gene mutation on clinical features of invasive lung adenocarcinoma." (PMID 41378298, 2025). "This study found a correlation between EGFR mutation status, ALK positivity, and demographic, tumor, radiological, and pathological features in lung adenocarcinoma patients." (PMID 41378298, 2025). "EGFR amplification in lung adenocarcinoma can be a de novo event or a secondary acquired resistant mechanism after targeted therapy." (PMID 40310364, 2025). "In conclusion, MCAM induced EGFR-TKI resistance in lung adenocarcinoma by interacting with Integrin β1 and then activating the JAK3 signalling pathway." (PMID 40713600, 2025). "Here, we present the first case showing the anti‐tumor efficacy of afatinib and the second case showing the anti‐tumor efficacy of osimertinib, respectively, in patients with EGFR L861R‐positive lung adenocarcinoma." (PMID 41350121, 2025). "In EGFR-mutant lung adenocarcinoma, the combination of EGFR inhibitor erlotinib and anti-PD-1 monoclonal antibody significantly inhibited tumor growth." (PMID 40861801, 2025). "This study aimed to explore the relationship between EGFR mutations, ALK positivity, and demographic, tumor, radiological, and pathological characteristics in lung adenocarcinoma patients." (PMID 41378298, 2025). "Here, we present the first case showing the anti‐tumor efficacy of afatinib and the second case showing the anti‐tumor efficacy of osimertinib in a patient with EGFR L861R‐positive lung adenocarcinoma." (PMID 41350121, 2025). "Lung adenocarcinoma is the most common histologic subtype of non-small cell lung cancer (NSCLC), with EGFR mutations detected in approximately 12%–38% of cases, particularly among East Asian populations and never-smokers." (PMID 41585239, 2025). "In this study, we initially employed the Maximum Relevance Minimum Redundancy (mRMR) algorithm to perform preliminary feature selection on CT imaging data from 106 patients with EGFR-mutant advanced lung adenocarcinoma." (PMID 40520794, 2025). "Activating mutations of the epidermal growth factor receptor (EGFR) gene act as an important oncogene for poor clinical outcomes and occur in about 50% of patients with lung adenocarcinoma in Asia." (PMID 41399957, 2025). "In this study, we identified TLSs in early-stage EGFR-mutant lung adenocarcinoma patients and investigated the relationship between disease-free survival (DFS) and TLS density in these patients." (PMID 40723259, 2025). "The most frequently mutated genes in lung adenocarcinomas are KRAS and Epidermal Growth Factor Receptor (EGFR), molecules in a common signaling pathway." (PMID 41002380, 2025). "EGFR represents the most frequent genetic alteration in lung adenocarcinoma, accounting for approximately 60% of cases in Asian populations." (PMID 40963567, 2025).
lung adenocarcinoma (continued). "High Hes1 expression also confers resistance to EGFR-TKIs (trametinib, lapatinib) in low-grade serous ovarian cancer, gastric cancer, and lung adenocarcinoma." (PMID 40755759, 2025). "In lung adenocarcinoma, EPHA5 expression is positively correlated with EGFR mutation status and lymph node metastasis, implicating its potential role in tumor progression and molecular classification." (PMID 40806980, 2025). "The proposed DL model predicts EGFR-mutant of lung adenocarcinomas accurately that help clinical decision-making by identifying eligible patients for therapy." (PMID 40078179, 2025). "There are no reports of histological partial transformation to SCLC in EGFR-driven lung adenocarcinoma." (PMID 40134592, 2025). "In this study, we focused specifically on early-stage EGFR-mutant lung adenocarcinoma and characterized the presence of TLSs within this subtype." (PMID 40723259, 2025). "This study investigates the prognostic value of TLSs and their molecular characteristics in early-stage EGFR-mutant lung adenocarcinoma." (PMID 40723259, 2025). "For example, primary tumor radiotherapy prolongs the survival of lung adenocarcinoma patients after disease control with EGFR-TKI, including both oligometastatic and multimetastatic patients." (PMID 40003899, 2025). "Here, we present the case of a patient with lung adenocarcinoma harboring EGFR and somatic BRCA2 mutations, who developed resistance to third-generation EGFR tyrosine kinase inhibitors (TKIs) and subsequently exhibited durable response to Olaparib." (PMID 40182045, 2025). "Regarding mechanisms, the AHSA1-HSP90AA1 complex stabilizes IFI6 and TGFB1 to enhance cell survival and Osimertinib resistance in EGFR mutant lung adenocarcinoma." (PMID 40234395, 2025). "The results showed that the IC50 of gefitinib or osimertinib decreased after MCAM knockdown in EGFR-TKI-resistant lung adenocarcinoma cells, indicating that the sensitivity to EGFR-TKIs was restored to a certain extent." (PMID 40713600, 2025). "Molecular testing identified an EGFR exon 19 deletion in both the intracranial lesion and the primary lung adenocarcinoma resected 14 years earlier, confirming a shared clonal origin." (PMID 41416296, 2025). "In HEK-293T cells, TGFB1 overexpression increased β-catenin and Snail expression, accompanied by a corresponding downregulation of E-cadherin and Vimentin, indicating that TGFB1 strongly promotes EMT in EGFR-mutant lung adenocarcinoma cells." (PMID 40234395, 2025). "In EGFR-mutant lung adenocarcinoma (LUAD), lineage plasticity is increasingly recognized as a prevalent mechanism of acquired resistance to tyrosine kinase inhibitors (TKIs)." (PMID 41516316, 2025). "In a series of lung adenocarcinoma patients metastatic to the spine with mutational data for selected markers (ALK, MET, ROS1, EGFR, and KRAS), the presence of clinically targetable mutations was found to be associated with increased survival." (PMID 40647516, 2025). "The majority of samples in our cohort were PD-L1-negative, aligning with real-world observations of EGFR-mutant lung adenocarcinoma." (PMID 40723259, 2025). "This study reveals the HIF1A-SLC16A3 axis is a key mediator of ferroptosis resistance and EGFR-TKI tolerance in lung adenocarcinoma." (PMID 41293164, 2025). "During the study, 2343 patients with advanced lung adenocarcinoma were diagnosed, including 1167 EGFR+, 327 ALK+, 98 ROS1+, and 56 RET+ patients." (PMID 40751559, 2025). "In-frame deletions of exon 19 of the EGFR gene lead to constitutive activation of EGFR tyrosine kinase activity and render the receptor sensitive to tyrosine kinase inhibitors (TKIs), such as gefitinib, erlotinib, and afatinib, in lung adenocarcinoma." (PMID 41142752, 2025).
lung adenocarcinoma (continued). "Schoenfeld and colleagues reported that 5 of 62 patients with EGFR‐mutant lung adenocarcinoma, progressing on first‐line Osimertinib, exhibited squamous transdifferentiation." (PMID 41415713, 2025). "Patients with epidermal growth factor receptor (EGFR)-mutant lung adenocarcinoma (LUAD) presenting with malignant pleural effusion (MPE) at diagnosis have a poor prognosis." (PMID 41479892, 2025). "Cnfirmed synchronous primary lung adenocarcinomas (EGFR G719C and exon 19 deletion) and thyroid cancer." (PMID 40855618, 2025). "Our previous study also demonstrated that resistin promotes lung adenocarcinoma metastasis through the TLR4/Src/EGFR/PI3K/NF-κB pathway." (PMID 40002704, 2025). "Pathology confirmed lung adenocarcinoma, and NGS testing detected an EGFR p.L833V/p.H835L compound mutation." (PMID 40963567, 2025). "Similar results were obtained in the human lung adenocarcinoma cells PC9 (EGFR mutant) displaying higher baseline TAP2 expression than A549." (PMID 40091029, 2025). "For instance, in EGFR-mutant lung adenocarcinoma, quantitative assessment of EGFR-pTyr1197 phosphorylation via targeted MS of liquid biopsy samples or immunohistochemistry on serial tumor biopsies provides a direct pharmacodynamic readout." (PMID 41306527, 2025). "The expression level of MCAM was significantly higher in EGFR-TKI resistant lung adenocarcinoma cells compared to EGFR-TKI sensitive lung adenocarcinoma cells." (PMID 40713600, 2025). "Multivariate analysis was conducted to investigate the association of these parameters with EGFR gene mutation and ALK gene rearrangement in patients with GGO-associated lung adenocarcinoma." (PMID 41020204, 2025). "The quantitative and qualitative parameters of three-dimensional CT are closely associated with EGFR gene mutations, ALK gene rearrangements, and prognosis in patients with GGO-associated lung adenocarcinoma." (PMID 41020204, 2025). "Combining chemotherapy with TKIs has been extensively studied in EGFR mutant lung adenocarcinoma, with FLAURA 2 study demonstrating overall survival benefit when used in the frontline setting and MARIPOSA-2 study in the second line setting, respectively." (PMID 40710887, 2025). "Epidermal growth factor receptor (EGFR) mutations and anaplastic lymphoma kinase (ALK) rearrangements are the most common druggable targets in lung adenocarcinoma." (PMID 41378298, 2025). "We describe the case of a woman in her 60s receiving osimertinib for EGFR L858R-mutant lung adenocarcinoma who developed new pulmonary lesions." (PMID 40502915, 2025). "The results of cell proliferation and cytotoxicity assays demonstrated that MCAM played a crucial role in conferring acquired resistance to EGFR-TKIs in lung adenocarcinoma cells." (PMID 40713600, 2025). "Background/Objectives: Acquired resistance to epidermal growth factor receptor (EGFR)-tyrosine kinase inhibitors (TKIs) remains a major challenge in the treatment of EGFR-mutant lung adenocarcinoma (LUAD)." (PMID 41599648, 2025). "CCK-8 cytotoxicity assay demonstrated that overexpression of MCAM enhanced resistance to EGFR-TKIs in EGFR-mutant lung adenocarcinoma cells." (PMID 40713600, 2025). "For patients with early-stage EGFR-mutant lung adenocarcinoma, surgery remains the standard treatment." (PMID 40723259, 2025). "We found that MCAM expression was increased in EGFR-TKI-resistant lung adenocarcinoma and was involved in the process of EGFR-TKI resistance." (PMID 40713600, 2025). "Molecular profiling for driver mutations such as EGFR, ALK, and ROS1 is essential in advanced lung adenocarcinomas." (PMID 40949067, 2025).
lung adenocarcinoma (continued). "Third, YY1 was analyzed in six cases of advanced EGFR-mutant lung adenocarcinoma with disease relapse following first-line EGFR inhibitor treatment, which showed that YY1 levels rebounded to baseline in recurrent tumors." (PMID 39604408, 2024). "Further studies on lung adenocarcinoma have demonstrated that the downregulation of GPSM2 accelerates cell proliferation through the EGFR pathway." (PMID 38674408, 2024). "Diagnostic workup, including immunohistochemical analysis and NGS, confirmed lung adenocarcinoma with an EGFR exon 19 deletion." (PMID 39334060, 2024). "PLC-PHM MPC incidence is rising, characterized by a significant proportion of lung adenocarcinoma and a high prevalence of positive driver genes, especially in EGFR." (PMID 38402182, 2024). "HCC827 lung adenocarcinoma cells were challenged with EGFR tyrosine kinase inhibitors in monolayer and spheroid culture." (PMID 38538642, 2024). "Here, we take a systems-biology approach, using proteomics and genomics to examine the development of drug tolerance to EGFR inhibitors in EGFR-mutant lung adenocarcinoma cells and BRAF inhibitors in BRAF-mutant melanoma cells." (PMID 38473364, 2024). "This study offers insights into genomic features of Chinese EGFR/ALK wild‐type lung adenocarcinoma patients based on PD‐L1 expression." (PMID 38396367, 2024). "Several reports have demonstrated significant anti-tumor responses to EGFR TKI treatment for lung adenocarcinoma patients with EGFR-KDD alterations, including gefitinib, erlotinib, afatinib, and osimertinib." (PMID 38974236, 2024). "In this retrospective study, tumor samples from 359 Chinese EGFR/ALK wild‐type lung adenocarcinoma patients underwent comprehensive evaluations for PD‐L1 expression and NGS‐targeted sequencing." (PMID 38396367, 2024). "Lung adenocarcinoma (LUAD) is the most common histological subtype of NSCLC, and approximately 15% of Caucasians and 50% of Asians harbor activating epidermal growth factor receptor (EGFR) mutations." (PMID 39090096, 2024). "High tumor mutational burden correlated significantly with PD‐L1 positivity in patients with EGFR/ALK wild‐type lung adenocarcinoma." (PMID 38396367, 2024). "Transdifferentiation toward an aggressive small-cell neuroendocrine cancer (SCNC) phenotype occurs in response to targeted therapies, for example, in resistance to epidermal growth factor receptor (EGFR) kinase inhibitors in lung adenocarcinomas." (PMID 39457647, 2024). "Here, we report a case of a lung adenocarcinoma patient presenting with ground-glass metastases, MSI-H, and EGFR-sensitive mutation and provide clinical data on the efficacy and prognosis." (PMID 39530096, 2024). "In lung adenocarcinoma, key oncogenes such as KRAS, EGFR, ALK, ERBB2, and BRAF are frequently mutated and are found in over 50% of cases." (PMID 39682234, 2024). "Recent Asian expert consensus has reported that the percentage of EGFR alterations in lung adenocarcinoma is higher among East Asian compared to Western population (40–55% vs. 12–25%), while KRAS, BRAF, and ROS1 are lower, with HER2 and MET are nearly similar." (PMID 38245692, 2024). "This study analyzed EGFR/ALK wild‐type lung adenocarcinoma patients to explore correlations between gene/pathway alterations and PD‐L1 TPS." (PMID 38396367, 2024). "Our previous study showed that YAP directly regulates the expression of PD-L1 transcripts and that the YAP/TEAD complex binds to the PD-L1 promoter in EGFR-TKI-resistant lung adenocarcinoma." (PMID 38339350, 2024). "In our previous research, we confirmed that miR-125 induces resistance to EGFR-TKIs in lung adenocarcinoma by upregulating its target gene Rab25 through the PI3K/AKT signaling pathway." (PMID 39196297, 2024).